GCAWKR (gastric cancer associated WDR5 and KAT2A binding lncRNA)
Gene: Long non-coding RNA gene on chromosome 15 (100,849,538 to 100,876,836, forward strand). Ensembl gene ENSG00000272808.
Diseases named in the same sentence as GCAWKR in open-access papers:
GCAWKR is named in the same sentence as 1 disease in open-access papers, as found by Europe PMC text mining. Sharing a sentence is not in itself a finding about the gene and the disease. The quoted sentences say what the papers report.
gastric cancer (2 papers, 2020 to 2022). A primary or metastatic malignant neoplasm involving the stomach. "Previous work has shown that the lncRNAs GClnc1 and GCAWKR can serve as scaffolds for KAT2A and WDR5 in gastric cancer, and can thereby serve as positive regulators of this enzyme." (PMID 31320749, 2020).